CYP24A1 (cytochrome P450 family 24 subfamily A member 1)
Diseases named in the same sentence as CYP24A1 in open-access papers (continued):
Sharing a sentence is not in itself a finding about the gene and the disease.
breast tumor (9 papers, 2010 to 2024). "Based on these genomic data, expression of the genes that encode VDR, CYP27B1, and CYP24A1 appears to be in the normal range for the vast majority of breast tumors." (PMID 34950835, 2021). "The mRNA expression of CYP24A1 in breast tumor tissue was significantly lower than that in breast normal tissue (p = 3.6e-10)." (PMID 31548577, 2019). "Specifically, cyp24a1 (1,25-dihydroxyvitamin D3 24-hydroxylase) was translationally upregulated in breast tumor cells treated with supernatants of activated monocyte-derived macrophages using polysome profiling and microarray analysis." (PMID 24416388, 2014). "Frequency of genomic alterations in VDR and CYP24A1 derived from The Cancer Genome Atlas dataset of human breast tumors." (PMID 24982636, 2014). "Using polysome profiling and microarray analysis, we identified cyp24a1 (1,25-dihydroxyvitamin D3 24-hydroxylase) to be translationally upregulated in breast tumor cells co-cultured with conditioned medium of activated monocyte-derived macrophages (CM)." (PMID 24416388, 2014). "It has been observed that both CYP27B1 and CYP24A1 are up-regulated in breast tumours when compared with normal tissue." (PMID 20831823, 2010). "Conversely, we have also demonstrated that COX-2 expression is higher in breast tumors with elevated expression of CYP24A1, an enzyme responsible for VD3 catabolizing, whereas tumors with high CYP27B1 expression (enzyme responsible for VD3 synthesis) exhibit lower COX-2 expression." (PMID 38355711, 2024). "The effects of 1,25(OH)2D3 0.5nM on the expression of CYP24A1, DPP4, IL1RL1, CD14, CA2 and BMP6, were further explored in breast tumor derived cells, representing the epithelial and stromal compartments, using RT-qPCR." (PMID 23497279, 2013).
multiple sclerosis (9 papers, 2013 to 2025). A progressive autoimmune disorder affecting the central nervous system resulting in demyelination. "It was shown that the risk allele rs2248359_C, which is associated with an increased expression of CYP24A1 in frontal cortex, increases the risk of multiple sclerosis, possibly by changing immunomodulation in brain." (PMID 37601072, 2023). "Moreover, a pathogenic role for CYP24A1 in multiple sclerosis and ischemic stroke has been proposed." (PMID 37601072, 2023). "We prioritized 186 cis-eQTLs for 31 brain-related traits using Mendelian randomization and co-localization including 40 cis-eQTLs with an inferred cell type, such as a neuron-specific cis-eQTL (CYP24A1) for multiple sclerosis." (PMID 36823318, 2023). "T cells from female subjects with multiple sclerosis have reduced expression of CYP24A1 transcripts." (PMID 23826346, 2013).
ovarian carcinoma (9 papers, 2013 to 2024). A malignant neoplasm originating from the surface ovarian epithelium. "High expression levels of CYP24A1, PPPIRIC, and FOXD3-AS1, detected in A2780CP20-RBPMSC clones, were associated with longer PFS (HR < 1) and better prognosis (OS; HR < 1) of ovarian cancer patients." (PMID 36499073, 2022).
thyroid cancer (9 papers, 2014 to 2022). "Loss of CYP24A1 therefore facilitated the anti-tumor efficacy of 1α,25(OH)2D3 in lung, colorectal, endometrial and thyroid cancer cells." (PMID 32850381, 2020). "The aim of this study was to determine if the DHCR7 rs12785878, CYP2R1 rs2060793, and CYP24A1 rs6013897 SNPs are also associated with susceptibility to thyroid cancer." (PMID 31357732, 2019). "Some associations between thyroid cancer risk (VDR, CYP24A1, DHCR7) or the clinical course of the disease (VDR) and vitamin D-related gene polymorphisms were described in the literature." (PMID 36362448, 2022). "Molecular studies have established clear connections between several targets in the vitamin D metabolism pathway and thyroid cancer, including CYP24A1 and VDR." (PMID 34298730, 2021). "On the other hand, in the mouse model of thyroid cancer, Cyp24a1 knockout led to a decline in tumorigenesis, which directly proved that Cyp24a1 functions as an oncogene." (PMID 33172201, 2020). "A similar trend was observed in thyroid pathology where increased CYP24A1 expression was found in follicular adenomas, while in differentiated thyroid cancers its level decreased, being comparable with normal tissues." (PMID 25334067, 2014). "It was characterized by the increased levels of VDR, CYP24A1 and CYP27B1 in benign and differentiated malignant thyroid tumors." (PMID 25501638, 2015). "Thyroid cancers with lymph-nodes and distant metastases had lower CYP24A1 expression in comparison to non-metastasizing cancers, and the lack of CYP24A1 in anaplastic thyroid cancer was accompanied by a higher proliferation rate." (PMID 25334067, 2014).
Hypertension (8 papers, 2014 to 2025). The presence of chronic increased pressure in the systemic arterial system. "Evidence relating to the association between CYP24A1 gene polymorphism and susceptibility to hypertension, especially among pregnant women, is scare." (PMID 35684156, 2022). "A case-control study among the Chinese Han population found that CYP24A1-rs56229249 significantly decreased the hypertension risk in homozygote and recessive models." (PMID 35684156, 2022). "We also investigated the other risk factors (age, gender, hypertension, coronary disease) of ischemic stroke related to polymorphism of CYP24A1 gene." (PMID 31872978, 2020). "In addition, we also examined the correlation between SNPs of CYP24A1 gene and ischemic stroke risk via stratification analysis including age, gender, hypertension, and coronary disease." (PMID 31872978, 2020). "In addition, CYP24A1 polymorphisms were associated with many diseases, such as stroke, hypertension, hepatitis C virus infection and cancers." (PMID 32762692, 2020). "Many studies revealed that genetic variants in CYP24A1 gene have previously been investigated in relation to risk of human diseases, such as coronary artery disease, hypertension, and obesity with ischemic stroke It can be seen CYP24A1 polymorphisms association with ischemic stroke susceptibility." (PMID 31872978, 2020). "Interestingly, CYP24A1 polymorphisms (rs1570669 and rs2296241) played a protective role in risk of ischemic stroke, especially for the patients with hypertension." (PMID 31872978, 2020). "In addition, we also analyzed the relationship between the SNPs in CYP24A1 gene and ischemic stroke risk on the basis of stroke potential risk factors including hypertension and coronary disease." (PMID 31872978, 2020). "A stepwise regression model was established comprising gender, age, visceral obesity, ALT, γ-GT, hypertriglyceridemia, hypertension, low HDL-C, hyperglycemia, and combined unfavorable alleles (CYP24A1 rs2296241-A, CYP24A1 rs2248359-T, and CYP27B1 rs4646536-T)." (PMID 34484304, 2021).
secondary hyperparathyroidism (8 papers, 2020 to 2024). Overproduction of parathyroid hormone in response to influence external to the parathyroid glands. "CYP24A1 has also been implicated in dysregulation of 1,25D in CKD, which contributes to development of secondary hyperparathyroidism." (PMID 39688907, 2024). "While additional investigation is needed to understand the mechanism of FGF23 reduction in VillinCreERT2Cyp24fl/fl mice with kidney damage, these results support inhibition of intestinal CYP24A1 as an approach to mitigate secondary hyperparathyroidism and FGF23 excess in patients with CKD." (PMID 39688907, 2024). "Intestinal CYP24A1 presents a new target for treatment of secondary hyperparathyroidism." (PMID 39688907, 2024). "Intestinal Cyp24a1 deletion mitigates secondary hyperparathyroidism in a mouse model of CKD." (PMID 39688907, 2024). "To test this hypothesis, we fed animals with intact Cyp24a1 an adenine-containing diet for 2 weeks to model CKD-induced secondary hyperparathyroidism." (PMID 39688907, 2024). "Finally, we hypothesized that reducing intestinal CYP24A1 effects would attenuate secondary hyperparathyroidism in CKD." (PMID 39688907, 2024). "Furthermore, our finding that intestine-specific Cyp24a1 deletion can attenuate secondary hyperparathyroidism in an established model of chronic kidney damage suggests that intestinal CYP24A1 could serve as a therapeutic target in CKD and, potentially, other disorders of mineral homeostasis." (PMID 39688907, 2024). "CYP24A1 upregulation in CKD and diminished activation of vitamin D3 contribute to secondary hyperparathyroidism (SHPT), progressive bone deterioration, and soft tissue and cardiovascular calcification." (PMID 35883516, 2022). "This elevation is due to 2 phenomena: (a) inactivation of the CYP27B1 enzyme — thus, no conversion — and, more importantly, (b) secondary hyperparathyroidism that suppresses the activity and expression of the Cyp24a1 gene and CYP24A1 enzyme." (PMID 38916957, 2024). "Cyp24a1 mRNA in M1/M21-KO mice is undetectable due to absent 1,25-vitamin D levels and dramatic secondary hyperparathyroidism." (PMID 36862513, 2023).
hypophosphatemia (7 papers, 2014 to 2024). Lower than normal levels of phosphates in the circulating blood. "More surprisingly, 27-28% of our patients with CYP24A1 biallelic mutations also presented with hypophosphatemia." (PMID 34721296, 2021). "Hypophosphatemia (serum phosphate Z-score < -2) was reported in 7 patients (27-28%) with CYP24A1 biallelic mutations and 1 patient with SLC34A3 biallelic mutations." (PMID 34721296, 2021). "Conversely, abnormally elevated CYP24A1 in certain disease states, such as hypophosphatemia and certain types of cancer associates with decreased vitamin D status and with vitamin D resistance." (PMID 25522365, 2014). "ii) Our data indicate that hypophosphatemia is not specific to phosphate wasting defects, also observed in CYP24A1 mutation, explaining a wide phenotypic overlap." (PMID 34721296, 2021). "Both hypophosphatemia and low FGF-23 levels increase Cyp27b1 and inhibit Cyp24a1 expressions and activities." (PMID 35414099, 2022). "Despite displaying hypophosphatemia and low serum calcitriol, mice with elevated FGF23 (Hyp or Fgf23-TG) did not develop skeletal abnormalities when CYP24A1 levels were repressed, either in Cyp24a1-null mutants or following blocking with CTA102." (PMID 30808384, 2019).
lung adenocarcinoma (7 papers, 2014 to 2025). A carcinoma that arises from the lung and is characterized by the presence of malignant glandular epithelial cells. "Recently, CYP24A1 has been studied in many diseases, and it is identified as a potential biomarker for cancers, including lung adenocarcinoma and colorectal cancer." (PMID 31548577, 2019). "Overexpression of CYP24A1 accelerated cell growth and cell invasion of lung adenocarcinoma cells." (PMID 34249502, 2021). "The expression of CYP24A1 is relevant to the poor prognosis of resected lung adenocarcinoma." (PMID 34323652, 2021). "CYP24A1 expression level was highly increased in lung adenocarcinoma compared to normal lung tissue samples and CYP24A1 overexpression was associated with poorer survival, increased cell growth and invasion, and increased RAS protein expression in lung adenocarcinoma." (PMID 32998690, 2020).
Obesity (6 papers, 2015 to 2021). Accumulation of substantial excess body fat. "A single SNP; rs2296239 in CYP24A1 showed association with just one obesity trait (waist-hip ratio), and even this association was significant in only one of the cohorts." (PMID 32534577, 2020). "The vast majority of the associations (56 associations) were identified in the vitamin D metabolism-related genes (CYP24A1, GC and VDR) and, in particular, the VDR gene SNPs showed 48 significant associations with obesity outcomes." (PMID 33553043, 2020). "In adipose tissue, CYP27B1 level is lower in obese than lean women, whereas CYP24A1 expression does not differ between them explaining obesity associated VD3 deficiency." (PMID 33095902, 2021). "Studies on CYP27B1, CYP24A1 and GC genes demonstrated a lack of association with obesity and T2D in Europeans; however, significant associations with T2D were found in South Asians." (PMID 33553043, 2020). "Three studies have examined the catabolism gene CYP24A1 SNPs; however, none of them showed a significant association with obesity traits." (PMID 33553043, 2020). "Moreover, vitamin D catabolism may be increased in obesity, as the 25OHD degrading enzyme CYP24A1 is increased in obese compared to lean subjects." (PMID 26085837, 2015).
gestational diabetes mellitus (5 papers, 2015 to 2024). "Gestational diabetes has been shown to increase the activity of CYP24A1 in the trophoblast, which metabolizes both 25(OH)D and 1,25(OH)2D to their inactive forms." (PMID 39035594, 2024). "Several studies have identified placental CYP24A1 upregulation in preeclampsia, gestational diabetes, and fetal growth restriction in women residing at low altitude." (PMID 36834800, 2023). "In the SB network, CYP24A1 was one of the well-connected genes and it has been shown to be significantly more expressed in placental tissue from women with gestational diabetes mellitus." (PMID 26830357, 2016).
oral cancer (5 papers, 2021 to 2025). "The CYP24A1 (rs2296241) heterozygote genotype significantly reduces oral cancer risk (OR = 0.281, P = 0.00001)." (PMID 40356850, 2025). "A notable reduction in oral cancer risk was seen in persons possessing the heterozygous genotype of the CYP24A1 gene (rs2296241) compared to the wild type." (PMID 40356850, 2025). "Upregulated CYP24A1 is associated with DTX resistance, and poor overall survival of oral cancer patients." (PMID 40385549, 2025).
osteoporosis (5 papers, 2017 to 2026). A condition of reduced bone mass, with decreased cortical thickness and a decrease in the number and size of the trabeculae of cancellous bone (but normal chemical composition), resulting in increased fracture incidence. "Genetic variations or single‐nucleotide polymorphisms (SNPs) in CYP27B1 and CYP24A1 have been associated with susceptibility to osteoporosis, as they modulate vitamin D availability and calcium signalling." (PMID 40831018, 2025). "Furthermore, AR could upregulate the expression of CYP27B1 and decrease the expression of CYP24A1, which indirectly increased the synthesis of VD in vivo, promoted osteogenesis, and alleviated the symptoms of osteoporosis." (PMID 34304712, 2021). "The multifactorial pathogenesis of osteoporosis involves complex interactions between genetic factors and vitamin D metabolism, particularly involving key genes such as the vitamin D receptor (VDR), CYP27B1 and CYP24A1." (PMID 40831018, 2025).
pancreatic cancer (5 papers, 2013 to 2022). "There are suggestions about the association between CYP24A1 SNPs and some cancer types, including prostate, breast, or pancreas cancer." (PMID 36362448, 2022). "For example, CYP24A1 rs6127119 TT versus CC genotype was positively associated with pancreas cancer risk (OR = 1.94; 95%CI: 1.28–2.94)." (PMID 23826131, 2013). "Consistent with the findings from the log-additive models, several SNPs in CYP24A1 and CYP2R1 were significantly associated with pancreas cancer risk, including CYP24A1 rs6127119 (TT versus CC." (PMID 23826131, 2013). "One reason leading to CYP24A1 overexpression in pancreatic tumors could be an activating mutation of K-ras." (PMID 25090635, 2014). "In this study, we show for the first time that CYP24A1 is overexpressed in pancreatic tumors on mRNA as well as on protein level." (PMID 25090635, 2014). "For example, pancreas cancer risk was inversely associated with CYP2R1 rs10741657 (AA versus GG, OR = 0.70; 95%CI: 0.51–0.95) and positively with CYP24A1 rs6127119 (TT versus CC." (PMID 23826131, 2013). "SNPs in the CYP24A1, CYP2R1, calcium sensing receptor (CASR), vitamin D binding protein (GC), retinoid X receptor-alpha (RXRA) and megalin (LRP2) genes were significantly associated with pancreas cancer risk." (PMID 23826131, 2013). "SNPs near the VDR (rs2239186), LRP2 (rs4668123), CYP24A1 (rs2762932), GC (rs2282679), and CUBN (rs1810205) genes were the top SNPs associated with pancreatic cancer (p-values 0.008–0.037), but none were statistically significant after adjusting for multiple comparisons." (PMID 25799011, 2015).
rickets (5 papers, 2010 to 2025). Bone softening and weakening usually caused by deficiency or impaired metabolism of vitamin D. Deficiency of calcium, magnesium, or phosphorus may also cause rickets. "Of note, monotherapy with active vitamin D or CYP24A1 inhibition alone ameliorate rickets in preclinical mouse models and may reduce the risk of secondary and tertiary hyperparathyroidism, supporting the use of the lowest possible dose of phosphate and higher doses of active vitamin D supplements." (PMID 33815294, 2021). "Thus, despite the limitations, different genotypes of BsmI SNP of the VDR gene modulated the expression of the VDR, CYP24A1, and SOD2 genes even though they did not alter the circulating levels of vitamin D in individuals with hypovitaminosis D." (PMID 37630755, 2023).
colitis (4 papers, 2018 to 2024). Inflammation of the colon. "In contrast, vitamin D analog BXL-62 showed significant reduction in proinflammatory cytokine expression such as TNF-α, and induced CYP24A1 expression in peripheral blood mononuclear cells in DSS-induced colitis in mice." (PMID 32422882, 2020). "The upregulation of CYP24A1 following Vitamin D supplementation may be disadvantageous and should be considered when treating colitis." (PMID 32422882, 2020). "Despite this elevated CYP24a1 expression, the MAC-CYP cell treatment could overcome this enhanced local 1,25(OH)2D catabolic mechanism and effectively suppress colitis." (PMID 39273035, 2024). "In those with colitis, the ratio of CYP27B1 to CYP24A1 may prove to be important for successful treatment." (PMID 32422882, 2020). "Together with vitamin D and its proposed anti-inflammatory properties, vitamin D may reduce colitis by regulating COX-2, TNF-α, NF-κB through IkBa expression, RXR signaling, and vitamin D-activating enzymes CYP24A1 and CYP27B1." (PMID 32422882, 2020). "Kidney CYP24A1 was up-regulated 4.5 ± 0.9 fold among D++ controls compared to D+ controls (p < 0.05) as an appropriate homeostatic mechanism, but there was no further increase with the induction of colitis." (PMID 30065252, 2018).